ALB (albumin)
Diseases named in the same sentence as ALB in open-access papers (continued):
Sharing a sentence is not in itself a finding about the gene and the disease.
Cirrhosis (continued). "Beyond its role as a plasma expander related to its oncotic properties, human albumin likely exerts many effects in decompensated cirrhosis that target the underlying pathophysiological mechanisms leading to HRS." (PMID 37510105, 2023). "Presence of SIBO (p = 0.028; HR = 4.2(1.2–14.9)) and serum albumin level (p = 0.027) were significant independent risk factors for death in cirrhosis." (PMID 37110440, 2023). "Albumin plays a role in neutrophil dysfunction, including defects in phagocytosis and basal ROS production, and is associated with bacterial infections in cirrhosis." (PMID 37822786, 2023). "A serum albumin ascites protein gradient greater than 1.1 is used to establish portal hypertension as the cause of ascites with cirrhosis, which is the most common cause of portal hypertension." (PMID 37013893, 2023). "In cirrhosis, the reduced response is associated with older age, stage of liver disease and systemic inflammation, and breakthrough infection with low albumin level." (PMID 37870985, 2023). "In patients with cirrhosis, on multivariate analysis, the risk of breakthrough infection was independently associated with lower albumin concentration (HR 0.47, 95% CI: 0.2-1.0, p = 0.0437)." (PMID 37870985, 2023). "Albumin exclusively binds bile acids for delivery to hepatocytes for processing and elimination; in cirrhosis, albumin loss contributes to increased serum bile acid concentrations." (PMID 37013893, 2023). "We found taking alcohol, HE, HS, cirrhosis, albumin and eGFR to be independent risk factors in the prevalence of infection in patients with HBV-ACLF." (PMID 35811816, 2022). "Many studies have now shown that noninvasive indicators, including platelet count, albumin, spleen size, and liver stiffness, are related to the severity of high-risk oesophagogastric varices and cirrhosis." (PMID 36510159, 2022). "Multivariate logistic regression analysis showed that taking alcohol, HE, HS, cirrhosis, albumin and eGFR were risk factors for the development of infection." (PMID 35811816, 2022). "The survivors and nonsurvivors were not significantly different in glucose, age, body mass index, sex, ethnicity, causes of cirrhosis, comorbidity, albumin, and length of ICU stay (P ≥ 0.05)." (PMID 35392026, 2022). "Compared to the HBV-CLD cohort, HBV-ACLF cohort had higher rates of cirrhosis, TBiL, and lower albumin that often increase HCC risk." (PMID 36339647, 2022). "In the study, multivariate logistic regression analysis showed that taking alcohol, HE, HS, cirrhosis, albumin and eGFR were risk factors for the development of infection in patients with HBV-ACLF." (PMID 35811816, 2022). "In patients with cirrhosis, alterations in the structures of circulating albumin caused by inflammation and redox changes are considered valuable biomarkers for evaluating oxidative stress." (PMID 36555935, 2022). "Based on a univariate analysis, the treatment method, albumin, serum bilirubin, platelet count, portal vein diameter, spleen thickness, varicose veins, cirrhosis and CSS score were associated with DFS (p < 0.05)." (PMID 34692526, 2021). "TIPS is more effective than LVP with albumin infusion for the treatment of refractory ascites associated with cirrhosis in terms of both ascites control and survival, but it is also more likely to cause hepatic encephalopathy." (PMID 34231046, 2021). "Various studies have identified certain laboratory variables as independent risk factors for mortality in cirrhosis and these include white cell count, creatinine, albumin, bilirubin, prolonged INR, and infections." (PMID 34166471, 2021). "Significant factors associated with post-treatment survival included cirrhosis, albumin, and creatinine level." (PMID 33777520, 2021). "According to the univariate analysis, the treatment method, albumin, serum bilirubin, platelet count, portal vein diameter, spleen thickness, varicose veins, cirrhosis and CSS were associated with OS (p < 0.05)." (PMID 34692526, 2021).
Cirrhosis (continued). "In one RCT, high dose albumin was associated with decreased risk of high grade overt HE compared to standard of care in patients with cirrhosis and ascites." (PMID 34575157, 2021). "We sought to determine the prognostic value of prothrombin time-international normalized ratio to albumin ratio (PTAR) in patients with hepatitis B virus-associated decompensated cirrhosis (HBV-DeCi)." (PMID 34055994, 2021). "Of note, previous studies identified some noninvasive models associated with mortality in patients with cirrhosis, including albumin-bilirubin score and C-reactive protein to albumin ratio." (PMID 34055994, 2021). "Treatment type, CP class A, cirrhosis, ascites, serum total bilirubin, serum albumin, ALBI grade, and serum AFP were strongly associated with OS in the univariate analysis." (PMID 34749663, 2021). "Multivariate analysis showed that hyperkalemia was associated with high dose spironolactone, low albumin levels (p-value:0.017), and advanced cirrhosis with a high Child-Pugh score (p-value: 0.003)." (PMID 34725608, 2021). "It has been shown that advanced cirrhosis is associated with a decrease in plasmatic albumin, thus it is an accepted clinical indicator for liver function." (PMID 33807462, 2021). "Cirrhosis-associated eigenmetabolite were significantly higher in NC and CC patients with high-albumin, which indicates the loss of liver anabolic function in cirrhotic AIH patients." (PMID 33777984, 2021). "The splenic size, platelet count, and albumin levels were independently associated with cirrhosis (p < 0.001, <0.001, and 0.003)." (PMID 33052263, 2020). "Albumin infusion was associated with a lower risk of rebleeding and in-hospital deaths in cirrhosis admitted for acute gastrointestinal bleeding." (PMID 32576140, 2020). "Cirrhosis, especially in advanced stages, is associated with a decrease in plasma albumin, and low albumin levels play a role in the formation of ascites." (PMID 33213378, 2020). "Some reports indicated that the increased risk of PVT in cirrhosis is associated with decreased liver function (Child–Pugh score B/C), low serum albumin, and increased prothrombin time." (PMID 32899804, 2020). "Albumin—decreased albumin levels are associated with cirrhosis, septal, intensive fibrosis, and steatohepatitis." (PMID 31979094, 2020). "This analysis demonstrates that albumin is cost-effective in terms of lives saved and QALYs gained in the management of decompensated cirrhosis associated with LVP, SBP, or HRS." (PMID 31278624, 2019). "Among them, 34 patients were confirmed to have underlying cirrhosis, manifested by older age, lower serum albumin, lower WCC, and platelet counts." (PMID 31191644, 2019). "Increased ASV exposure is a predictor of drug-induced injury and correlates with increased AST/ALT/bilirubin, decreased albumin levels, and cirrhosis associated with lower ASV clearance." (PMID 31291311, 2019). "The results of this analysis demonstrate that the use of albumin in the management of decompensated cirrhosis associated with LVP, SBP, or HRS results in lower total costs and improved clinical outcomes compared to other fluids." (PMID 31278624, 2019). "Of the albumin, GGT, and PLT established by this model, PLT and albumin have been confirmed to be associated with the severity of cirrhosis." (PMID 30186822, 2018). "According to univariate analyse, HBV, HBV-DNA, age, Child-Pugh score, AST, ALT, PLT, fibrosis-4, AST/ALT, APRI, Lok index, King score, and albumin were associated with cirrhosis." (PMID 30057907, 2018). "Among patients with cirrhosis, only admission serum albumin level ≤2.4 mg/dL was associated with risk of HAKI (2.60-fold)." (PMID 29927987, 2018). "In humans, a threefold increase in the level of MG-H1 residue content in plasma protein in cirrhosis was linked to a decrease in the concentration of plasma albumin and catabolism." (PMID 29456458, 2018).
Cirrhosis (continued). "After adjusting for potential confounders, admission serum albumin ≤2.4 mg/dL were associated with an increased risk of HAKI in patients with cirrhosis with adjusted OR of 2.60 (95% CI 1.32–5.21)." (PMID 29927987, 2018). "Because the ascites from subjects with cancer are exudates, while the ascites caused by cirrhosis are transudates, we measured the concentrations of total protein (TP) and albumin (ALB)." (PMID 28143894, 2017). "In contrast, the results indicated that higher serum GP73 levels were independently associated with several fibrosis/cirrhosis relevant parameters, such as higher gamma glutamyl transpeptidase, total bile acid, PT and lower albumin, respectively." (PMID 28157705, 2017). "The patient did have a low albumin secondary to cirrhosis causing low synthesis; therefore, the calcium level was corrected and it remained within normal range." (PMID 28589153, 2017). "Decompensated cirrhosis is associated to extensive post-transcriptional changes of human albumin (HA)." (PMID 27782157, 2016). "Univariate logistic regression analysis demonstrated that patients' high serum IgA and IgG, low platelets, low albumin, and old age were significantly associated with cirrhosis." (PMID 27123003, 2016). "Decreased plasma albumin levels indicate chronic liver failure caused mainly by cirrhosis, a late stage of hepatic fibrosis that results in widespread distortion of the normal hepatic architecture." (PMID 27046059, 2016). "Multivariate analysis with Cox-proportional hazards models finally indicated initial presence of cirrhosis (HR = 6.13, P = 0.012) and low serum albumin level (HR = 9.17, P = 0.002) as significant risk factors for liver-related death." (PMID 27656205, 2016). "Initial presence of cirrhosis, low platelet count (<130,000/mm3), and low serum albumin level (<3.0 g/dL) were significant risk factors associated with liver-related mortality on univariate analysis." (PMID 27656205, 2016). "Multivariate logistic regression analysis showed that serum IgA, albumin, and platelets were independent risk factors for cirrhosis." (PMID 27123003, 2016). "Other variables including age, cause of cirrhosis, albumin, sodium, platelets, Child–Pugh score, and diameter of the portal vein were not significant factors in univariate analysis." (PMID 24322305, 2014). "Univariate logistic regression analysis showed significant associations between cirrhosis and markers, including albumin, globulin, CHE, PT, INR, PLT, AFP, and CP (all P-values<0.05)." (PMID 24282481, 2013). "Our study demonstrated that TSP-1, Gal-3, and Cys-C independently increased the risk of death in compensated cirrhosis, whereas albumin and plasminogen activity could act as protective factors." (PMID 40417691, 2025). "With that, several studies have investigated whether long-term albumin infusion would improve the control of ascites and as well alter the natural course of underlying cirrhosis." (PMID 40143117, 2025). "In addition, increasing serum albumin levels by branched-chain amino acid supplementation is a promising treatment option for patients with cirrhosis associated HE." (PMID 40928524, 2025). "Indeed, serum albumin levels have been reported to stratify the risk of developing OHE in patients with cirrhosis in the United States and in Asia, which is consistent with our findings in the present study." (PMID 40928524, 2025). "For example, cirrhosis is associated with impaired hepatic albumin synthesis, and nephrotic syndrome leads to urinary loss of albumin and globulins, both of which could result in falsely altered IPR values." (PMID 40362613, 2025). "Alterations in the structure and function of albumin are linked to conditions such as cirrhosis." (PMID 40281590, 2025). "If creatinine is < 1 mg/dL and bilirubin is < 4 mg/dL, then albumin infusion may be unnecessary because this group of cirrhosis patients are at a low risk of developing severe complications like renal failure." (PMID 38551716, 2024).
Cirrhosis (continued). "This review evaluates how albumin infusion ameliorates cirrhosis-associated complications." (PMID 38551716, 2024). "The finding that baseline albumin levels were associated with short-term improvement in liver fibrosis is similar to that of a previous report, in which the authors observed an association between albumin levels and improvement in liver function among patients with cirrhosis." (PMID 38808546, 2024). "Moreover, analysis of albumin-associated lipid mediators showed that patients with acute, uncompensated cirrhosis at risk of disease progression to ACFL have low levels of anti-inflammatory lipid mediators." (PMID 39273468, 2024). "The independent risk factors of mortality were CHF, cirrhosis, creatine kinase, and albumin." (PMID 38606387, 2024). "Furthermore, in patients with Child-Pugh class C cirrhosis, albumin infusion was associated with a decreased number of in-hospital deaths." (PMID 39151488, 2024). "In the CHB group, only low levels of albumin (0.719, 95% CI [0.545, 0.948], p = 0.019) and low levels of platelets (0.988, 95% CI [0.985, 0.992], p < 0.001) were significantly associated with the presence of cirrhosis." (PMID 38138039, 2023). "Moreover, the aim of our study was to determine the degree of association between the levels of albumin-corrected total serum calcium and abnormal liver function parameters in cirrhosis." (PMID 37371636, 2023). "The current findings show that sarcopenia is common in patients with cirrhosis and is independently associated with age, physical activity, BMI, nutritional status, and albumin, and serum alkaline phosphatase and total cholesterol are associated with the development of sarcopenia." (PMID 38071233, 2023). "Taken together, these data suggest that certain subgroups of patients with advanced cirrhosis may benefit from targeted albumin therapy, but in others, this may cause harm." (PMID 37019645, 2023). "The status of cirrhosis might be associated with ALB, AST and DBIL levels, which might contribute to multicollinearity." (PMID 37847433, 2023). "The addition of albumin to incubation media has been shown to decrease the number of neutrophils with high basal ROS production and reverse phagocytic capacity defects caused by plasma from patients with cirrhosis." (PMID 37822786, 2023). "Patients with cirrhosis and hyponatremia scheduled for LT are at risk for osmotic demyelination syndrome postoperatively because of the rapid rise in serum sodium associated with the use of large volumes of albumin solutions." (PMID 37218881, 2023). "Interestingly, neutrophil to albumin ratio is linked to mortality in patients with decompensated cirrhosis." (PMID 37822786, 2023). "After adjusting for a variety of clinical characteristics, cirrhosis was significantly associated with albumin (adjusted odds ratio (aOR) 0.85; 95% CI, 0.74–0.97, p=0.019), G stage (aOR 5.55; 95% CI, 1.56–19.67, p=0.008), and sGDNF (aOR 6.98; 95% CI, 1.10–17.94, p=0.036)." (PMID 35855954, 2022). "It seems that albumin infusions are unable to overcome the functional changes in circulating albumin caused by decompensated cirrhosis and that precision fluid resuscitation may be required to treat the complex cardiovascular phenotype of these patients." (PMID 35333783, 2022). "Additionally, higher disease severity, including low albumin, coexistence of cirrhosis, and high α-fetoprotein, led to a lower risk of all-cause mortality." (PMID 36231778, 2022). "The 20% albumin prepared from human plasma injection can be used to treat shock due to blood loss or burns, elevated cranial pressure due to cerebral edema and injury, or edema or ascites due to cirrhosis and renal disease." (PMID 36225556, 2022). "In patients with decompensated cirrhosis, serum albumin shows structural abnormalities, most often involving reversible oxidation and glycation, which lead to impaired binding capacity in albumin and increased risk of liver failure." (PMID 33925831, 2021).
Cirrhosis (continued). "Some studies have concluded that a decreased ALB level may be associated with an increased risk of OHE during hospitalization in cirrhosis patients." (PMID 34055016, 2021). "Furthermore, lower albumin levels were shown to be associated with increased risks of developing portal vein thrombosis in cirrhosis." (PMID 32379785, 2020). "The most common cause for a low albumin is chronic liver failure due to presence of cirrhosis." (PMID 33369474, 2020). "Linear regression analysis by stepwise method revealed that splenic size (cm), platelet count, and albumin levels were independently associated with cirrhosis with p-values of <0.001, <0.001, and <0.003 and Beta coefficients of 0.391, -0.356, and -0.221, respectively." (PMID 33052263, 2020). "In humans, reduced albumin to globulin ratios (driven by reduced albumin and increased globulins) are seen in individuals with chronic liver diseases associated with parenchymal damage, such as cirrhosis and liver cancer." (PMID 32995005, 2020). "Second, detailed laboratory data allowed us to differentiate the risk of HCC incidence, showing that age > 70, male sex, cirrhosis, treatment-experienced, serum albumin < 3.5 g/dL at pw12, and AFP > 7 ng/mL at pw12 were significantly associated with the development of HCC." (PMID 32933027, 2020). "Increased free PGE2 levels, due to decreased effective binding capacity of albumin, might therefore explain the profound immunodeficiency and associated bacterial infections typical of acutely decompensated cirrhosis." (PMID 30155448, 2018). "Notably, a low serum albumin level, which is universally associated with advanced stage of cirrhosis, has been well reported to be a predictor of severe or recurrent CDI." (PMID 27034681, 2016). "Cirrhosis was associated with age (p = 0.0026), BMI values (p = 0.0274), albumin levels (p < 0.0001), platelet counts (p < 0.0001), prothrombin times (p < 0.0001), hyaluronic acid levels (p < 0.0001), AFP levels (p < 0.0001), and the presence of HCC (p = 0.0017)." (PMID 25713769, 2015). "The most common reason for a low albumin is chronic liver failure caused by cirrhosis." (PMID 21194423, 2010). "In addition, increased PGE2 levels in patients with acute, uncompensated cirrhosis and who received albumin may be associated with a higher risk of inflammation during the first few days after hospitalization." (PMID 39273468, 2024). "Albumin may exacerbate lung edema in patients with chronic heart failure and increase bleeding risk due to hemodilution, as observed in hospitalized septic patients with cirrhosis." (PMID 38139434, 2023). "Moreover, the factors associated with mortality included abstinence, ALDH2 rs671 polymorphism, factors related to the severity of cirrhosis, such as Child-Pugh class and serum albumin, and newly developed HCC in patients with cirrhosis with HBV infection and alcoholism." (PMID 35877121, 2022). "The close association of cirrhosis with an increased risk of HCC development may provide an explanation for the stronger prognostic performance of combining the serum albumin level and the deletion spanning the pre-S2 gene segment for HCC recurrence after curative surgical resection." (PMID 34575311, 2021). "A low A/G ratio may be due to an overproduction of globulin, underproduction of albumin, or loss of albumin, which may indicate the following: an autoimmune disease, cirrhosis involving inflammation and scarring of the liver, multiple myeloma, and nephrotic syndrome, a kidney disease." (PMID 31662844, 2019). "Notably, multiple Asian studies identified several factors associated with adverse outcomes, including preexisting cirrhosis, prolonged PT, elevated bilirubin, elevated serum ferritin, low albumin, low platelet count, and the presence of encephalopathy or ascites." (PMID 25960593, 2015).